ANKRD45 (ankyrin repeat domain 45)
Description:
May play a role during cell division.
Synonyms: FLJ45235; CT117
Tractability: Antibody: its Gene Ontology location is reachable by antibodies, with high confidence.
Gene: Protein-coding gene on chromosome 1 (173,608,336 to 173,669,851, reverse strand). Ensembl gene ENSG00000183831.
Subcellular location: Cytoplasm; Midbody, Midbody ring; Cleavage furrow
Subcellular location (Human Protein Atlas): Cytosol; Centrosome; Plasma membrane
Gene Ontology:
Molecular function: protein binding
Biological process: cell population proliferation
Cellular component: cleavage furrow; cytoplasm; cytosol; midbody; Flemming body
Genetic constraint (gnomAD): Loss-of-function variants: 21 observed, 27.02 expected, observed/expected ratio (o/e) 0.78, 90% interval 0.55 to 1.12. The upper end of that interval is the gene's LOEUF score, 1.12, which puts it in group 4 of 6, group 1 being the genes least tolerant of losing a copy. Missense variants: 234 observed, 289.36 expected, observed/expected ratio (o/e) 0.81, 90% interval 0.73 to 0.9. Synonymous variants: 78 observed, 96.86 expected, observed/expected ratio (o/e) 0.81, 90% interval 0.67 to 0.97.
Homologues: Orthologues: chimpanzee ANKRD45 (99% identical), macaque ANKRD45 (97% identical), pig ANKRD45 (82% identical), rat Ankrd45 (75% identical), mouse Ankrd45 (74% identical), zebrafish ankrd45 (35% identical), tropical clawed frog ankrd45 (34% identical), Caenorhabditis elegans tnsl-1 (23% identical), Drosophila melanogaster Tnks (23% identical). Paralogues in human: TNKS (28% identical), TNKS2 (27% identical).
Diseases named in the same sentence as ANKRD45 in open-access papers:
ANKRD45 is named in the same sentence as 5 diseases in open-access papers, as found by Europe PMC text mining. Sharing a sentence is not in itself a finding about the gene and the disease. The quoted sentences say what the papers report.
gastric adenocarcinoma (1 paper, 2024). "For the individual gene, NDUFA4L2 and ANKRD45 were upregulated in the gastric adenocarcinoma, and were negatively correlated with the OS." (PMID 39409106, 2024). "The gene signature consisting of the NDUFA4L2, ANKRD45, and AQP3 genes is a promising biomarker to distinguish the prognosis, the molecular and immune characteristics, the depressive risk, and the therapy candidates for gastric adenocarcinoma patients." (PMID 39409106, 2024). "The relationship between NDUFA4L2, ANKRD45, and AQP3 with the clinicopathologic characteristics of gastric adenocarcinoma was presented with the heatmap." (PMID 39409106, 2024). "The signature based on the NDUFA4L2, ANKRD45, and AQP3 genes was evaluated with the area under curve (AUC) and nomogram-predicted probability, and the signature showed an ideal value to predict the OS of gastric adenocarcinoma." (PMID 39409106, 2024).
hepatoma (1 paper, 2019). "First, we analyzed subcellular localization of ANKRD45 using human hepatoma Hep3B cells." (PMID 31208154, 2019). "Similarly, ANKRD45 is also important for cell proliferation in several cancer cells, including human hepatoma Hep3B cells, which are relatively similar to the KrasG12V-induced liver cells." (PMID 31208154, 2019).
tumor (4 papers, 2017 to 2025). "Under stress conditions, such as rapid cell division in tumor cells, which might require high ANKRD45 levels, the gene regulation systems fail to fully compensate for the loss of ANKRD45, which eventually leads to cell apoptosis." (PMID 31208154, 2019). "The IHC signals for NDUFA4L2 and ANKRD45 were stronger in tumor tissue treated with CUMS, while AQP3 expression was weaker compared to the control, and the mRNA levels of signature genes are consistent with the IHC results." (PMID 39409106, 2024). "Sodium bisulfite sequencing (BSP) was used to validate the 6 randomly selected candidate islands, in which the results of 5 mapped genes (ANKRD45, CDX1, APC, HOXD3 and TUBB6) showed significant differences in the 10 pairs of validation tumor and adjacent tissue cohorts." (PMID 28418032, 2017).
cancer (2 papers, 2017 to 2019). A tumor composed of atypical neoplastic, often pleomorphic cells that invade other tissues. "The high requirement of ANKRD45 during cancer cell proliferation may be worthy of further attention to evaluate the potential target effects during therapeutic trials." (PMID 31208154, 2019). "Considering that high levels of KrasG12V expression can lead to hepatocellular carcinoma (HCC) in zebrafish and that KRASG12V is also the most popular mutation driving cancer cell proliferation, we further analyzed the role of ANKRD45 using several human cancer cells." (PMID 31208154, 2019). "We studied the expression level of the ANKRD45 and HOXD3 genes in cancer tissue and adjacent tissue using quantitative PCR." (PMID 28418032, 2017).
ANKRD45 also shares sentences with these, for which no sentence is quoted: synovial sarcoma (1 paper).